BRAF (B-Raf proto-oncogene, serine/threonine kinase)
Diseases named in the same sentence as BRAF in open-access papers (continued):
Sharing a sentence is not in itself a finding about the gene and the disease.
follicular adenomas (26 papers, 2009 to 2025). "Similar to previous reports, we found BRAF p.K601E in follicular variant PTC (four cases) as well as in one case of follicular adenoma." (PMID 36835466, 2023). "Specifically, the BRAF p.K601E mutation has been reported in follicular adenoma, while BRAF p.V600K has been reported in encapsulated follicular variant PTC." (PMID 32059434, 2020). "BRAF non p.V600E mutations were identified in two of four follicular adenomas that coexisted with the PTC." (PMID 32059434, 2020). "The indeterminate category is mainly constituted of FVPTC, FTC, adenomatoid hyperplasia, and follicular adenoma, all of which harbor low prevalence of BRAF mutation." (PMID 28472764, 2017). "BRAF mutations were detected in 15/199 (8%), and a BRAF K601E mutation was identified in 2 follicular adenomas and 1 noninvasive follicular thyroid neoplasm with papillary-like nuclear features." (PMID 29085338, 2017). "There were 2 benign nodules and one follicular adenoma nodule showing the BRAF mutation by ddPCR with very low fractional abundance (<2.00%), which could not be confirmed by histological pathology since these three patients did not receive surgery." (PMID 35392249, 2022). "MiR-181c-5p was found to be associated with the BRAF mutation in thyroid follicular adenomas." (PMID 34698264, 2021). "However, the other BRAF mutation, K601E, has been detected in follicular adenoma, carcinoma, and follicular variants of PTC." (PMID 34345541, 2021). "Indeed, its expression is upregulated in RAS- or BRAF-mutated follicular adenomas compared to wild-type tumors." (PMID 34698264, 2021). "Fluorescence in situ hybridisation study revealed that BRAF activation includes copy number gain and is present in 35% of FTCs, 25% of follicular adenomas (FAs), and 3% of PTCs." (PMID 39558949, 2024). "One BRAF V600E-positive case was detected by using real-time PCR and sequencing, and was confirmed as follicular adenoma after surgery." (PMID 32781560, 2020). "BRAF mutations were always associated with cancer, whereas RAS mutations were mainly associated with cancer (74–88%), but also with follicular adenoma (26%)." (PMID 28493027, 2017). "Others, instead of BRAF, frequently display RAS mutations, which are typically detected in follicular thyroid adenomas, FTC and fvPTC." (PMID 19809427, 2009). "No BRAF mutations were detected in benign nodular goiter, follicular adenomas, FV-PTC, or medullary carcinoma." (PMID 41303583, 2025). "Positive testing for BRAF or RET/PTC mutation has been shown to be specific for a malignant outcome in 100% of cases, whereas RAS mutations have been detected in up to 48% of benign follicular adenomas, 57% of FTC, and 21% of PTC." (PMID 35625691, 2022). "There were 5 nodules that belong to other cytological categories, including 2 nodules suspicious for PTC, 1 follicular adenoma, and 2 benign nodules, carrying BRAF V600E mutation detected by ddPCR but not by Sanger sequencing." (PMID 35392249, 2022). "A BRAF mutation was also found in the mPTC but not detected in the follicular adenoma or normal adjacent tissue." (PMID 25988151, 2014). "This is consistent with previous reports since benign follicular adenoma has not been found to harbor the BRAF mutation." (PMID 24252159, 2013). "Among the two BRAF K601E-positive cases, one was invasive FV-PTC and one was follicular adenoma, and BRAF K601E has been reported as a predictor for FV-PTC with a probability of 33–90%." (PMID 32781560, 2020). "PTCs, follicular adenomas, and minimally invasive FTCs from the TCGA cohort were classified into BRAF V600E-like, RAS-like, and non-BRAF/non-RAS types with different biological behaviours." (PMID 37374164, 2023).
keratoacanthoma (25 papers, 2012 to 2025). A dome-shaped, rapidly growing skin lesion composed of well differentiated squamous cells. "Certain drugs modulate risk: BRAF inhibitors can trigger eruptive keratoacanthomas/cSCC via paradoxical MAPK activation in RAS-mutant keratinocytes, an effect mitigated by MEK co-inhibition, while long-term voriconazole and vismodegib have also been linked to increased cSCC incidence." (PMID 41463022, 2025). "Squamoproliferative conditions, in particular keratoacanthomas, are frequently reported with BRAF inhibitors." (PMID 37513847, 2023). "Keratoacanthoma and Squamous Cell Carcinoma of the Skin: A distinct feature of the BRAF inhibitors is their ability to induce secondary cutaneous malignancies, such as keratoacanthomas (KAs) and cSCCs." (PMID 26328215, 2014). "It has been proposed that hyperproliferative skin lesions (keratoacanthomas) and in some cases SCC in BRAF inhibitor-treated patients were caused by pERK upregulation in wild-type BRAF cells, with a high RAS mutation frequency." (PMID 23844038, 2013). "The development of VP, keratoacanthomas and SCC in patients taking BRAF inhibitors has been thoroughly described." (PMID 25360634, 2014).
rectal tumors (25 papers, 2011 to 2026). "A study in the United States reported that NRAS mutations were associated with rectal tumors and BRAF mutations to old age in agreement with our findings." (PMID 32628708, 2020). "KRAS and BRAF wild-type cases were slightly younger at diagnosis and more often had rectal tumors compared to the KRAS-mutated cases." (PMID 32210264, 2020). "Among studies that separated rectal tumors from left‐sided tumors, the summary prevalence of RAS, KRAS, and BRAF mutations among rectal tumors was 34.3%, 30.8%, and 8.8%, respectively." (PMID 31856410, 2020). "These values contrast significantly with the previously reported 5-10% BRAF mutation rate, probably due to the fact that colon (both sides) and rectal tumors were grouped together in previous studies." (PMID 29156800, 2017). "BRAF mutations were seen in 25% of right-sided colon, 7% of left-sided colon, and 3.2% of rectal tumors." (PMID 29156800, 2017). "BRAF gene mutations were more than twofold more frequent on the right than on the left side (15.2% vs. 6.4%) and significantly more frequent in right-sided tumors than in rectal tumors (15.2% vs. 1.6%, p < 0.0001)." (PMID 38409377, 2024). "In line with previous studies, both BRAF-V600Emt and dMMR were more common in right colon tumours than in left colon or rectal tumours." (PMID 40437037, 2025). "Rectal tumors exhibit distinctive biological characteristics when compared to left-sided tumors, including a higher absence rate of KRAS, NRAS, and BRAF mutations (47.4% in rectal versus 42.8% in left-sided tumors)." (PMID 38409377, 2024). "Right-sided tumors had a higher frequency of BRAF and PIK3CA mutations compared to left-sided and rectal tumors." (PMID 30479693, 2018). "BRAF and PIK3CA mutations were more frequently noted in right-sided compared to left-sided colon and rectal tumors (chi-square, p=0.020 and p=0.018, respectively)." (PMID 30479693, 2018). "KRAS/BRAF wild-type cases were characterized by a lower age at diagnosis and a higher proportion of rectal tumors." (PMID 29694444, 2018). "Hutchins reported that KRAS mutant tumors were more evenly distributed: 40% right colon, 28% left colon, and 36% rectal tumors compared to BRAF mutant tumors." (PMID 22206623, 2011). "The difference between BRAF‐mutated and wild‐type OR point estimates was also retained for rectal tumors (but not for distal tumors) and among both men and women, but without reaching significance." (PMID 35383926, 2022). "Mucinous rectal tumors are more likely to be MSI-H, BRAF mutated and KRAS mutated which could potentially result in an impaired response to cytotoxic chemotherapy and EGFR inhibitors although this is only a hypothesis and needs to be confirmed prospectively with a much larger cohort." (PMID 32984045, 2020). "Moreover, high expression levels of PAI1 are associated with increased metastasis and invasion of rectal tumors in this cohort and TCGA database, respectively, which is correlated with EMT-associated and drug target genes expression, including PDGFRa, PDGFRb, FYN, PIM1 and BRAF." (PMID 32344898, 2020). "Positive expression, in comparison to negative expression, was related to rectal tumours and BRAF wild type regarding nuclear expression and BRAF wild type and secondary surgery regarding cytoplasmic expression." (PMID 28800641, 2017).
Hypertension (24 papers, 2015 to 2026). The presence of chronic increased pressure in the systemic arterial system. "An increased risk of cardiotoxicity, especially LVEF reduction (5–11%), hypertension (11–30%), or QT prolongation (0–5%), was highlighted with BRAF and MEK inhibitors treatment." (PMID 39859270, 2025). "In our study, we found that the variables that had the strongest association with survival were initial radical treatment, the number of cycles of first- and second-line chemotherapy, BRAF mutation status, and the presence of hypertension." (PMID 37318592, 2023). "BRAF mutation, radical treatment initially, the number of cycles of first- and second-line treatment and hypertension were incorporated into the survival prediction model." (PMID 37318592, 2023). "In conclusion, we have established a prognostic model for refractory mCRC treated with Trifluridine/Tipiracil based on five variables: initial radical treatment, the number of cycles of first- and second-line chemotherapy, BRAF gene mutation status, and presence of hypertension." (PMID 37318592, 2023). "Reduced bioavailability of NO may be implicated in the development of BRAF/MEK inhibitor–associated hypertension." (PMID 35492830, 2022). "Here, we used mice with tamoxifen-inducible cardiomyocyte-specific BRAF knockout (CM-BRAFKO) to assess the role of BRAF in hypertension-associated cardiac hypertrophy induced by angiotensin II (AngII; 0.8 mg/kg/d, 7 d) and physiological hypertrophy induced by phenylephrine (40 mg/kg/d, 7 d)." (PMID 36331065, 2022). "A meta-analysis including 5 randomized clinical trials reported an increased risk of systemic hypertension (RR: 1.49; 95% CI: 1.12-1.98]) that occurred in 19.5% of patients treated with combination of BRAF inhibitor and MEK inhibitor compared with 14% in the BRAF inhibitor monotherapy group." (PMID 35492830, 2022). "We have used the same dose in previous experiments including an assessment of the effects of dabrafenib (a BRAF inhibitor) on AngII-induced hypertension, in which we also demonstrated how the disease progresses towards heart failure over 28 d." (PMID 38718356, 2024). "Additional studies are needed to better define the role of BRAF under conditions reflective of chronic stress on the heart due to the biomechanical stimulation exerted by hypertension." (PMID 36651286, 2023). "BRAF and MEK inhibitors are associated with adverse cardiovascular effects including hypertension, left ventricular dysfunction, venous thromboembolism, atrial arrhythmia, and electrocardiographic QT interval prolongation." (PMID 35492830, 2022). "Hypertension is the most common adverse event reported with BRAF inhibitor and MEK inhibitor, and the incidence is higher with combination therapy." (PMID 35492830, 2022). "In a practical overview of multisystem toxic effects of BRAF inhibitor/MEK inhibitor therapy, Welsh and Corrie10 provide suggestions for the management of BRAF inhibitor– and MEK inhibitor–associated hypertension." (PMID 35492830, 2022). "We assessed the effects of BRAF knockout in a model of hypertension induced by treatment with 0.8 mg/kg/d AngII over 7 d." (PMID 36331065, 2022). "•Hypertension is the most commonly reported CVAE associated with BRAF and MEK inhibitors, and the incidence is higher with combination therapy versus BRAF inhibitor monotherapy." (PMID 35492830, 2022). "Given that BRAF inhibitors and MEK inhibitors are increasingly used in the adjuvant setting, adequate monitoring and treatment of hypertension is of even greater importance to reduce the risk of developing cardiovascular disease in the longer term." (PMID 35492830, 2022). "In two independent real‐world cohorts, combination BRAF/MEK inhibitors were associated with increased CVAEs compared to monotherapy, especially HF, and hypertension." (PMID 33982883, 2021).
Hypertension (continued). "In two independent real‐world cohorts, combination BRAF/MEK inhibitors were associated with increased cardiovascular adverse events compared to monotherapy, especially HF, and hypertension." (PMID 33982883, 2021). "Although dabrafenib had no obvious effect in an unstressed heart, it inhibited cardiac adaptation to AngII-induced hypertension suggesting BRAF signalling is important in disease development." (PMID 34296750, 2021). "More specifically, a BRAF/MEK inhibitor combination therapy resulted in a higher incidence of LVEF reduction (8.1% versus 2% for monotherapy) and hypertension (19.5% versus 14% for monotherapy) than BRAF monotherapy." (PMID 32405737, 2020). "BRAF had the highest risk of high-grade arthralgia (0.39%), whereas MEK had the highest risk of high-grade hypertension (2.28%) and nausea (0.37%)." (PMID 33178599, 2020). "In conclusion, therapy with BRAF and MEK inhibitors was associated with an increased risk of CVAEs, especially pulmonary embolism, a decrease in LVEF, and arterial hypertension, compared with BRAF inhibitor monotherapy." (PMID 31397860, 2019). "Cardiovascular adverse events (CVAEs) associated with BRAF and MEK inhibitors have been reported in several studies, particularly regarding a reduction in left ventricular ejection fraction (LVEF), arterial hypertension, and prolongation of QTc interval." (PMID 31397860, 2019). "In another meta-analysis of 5 randomised clinical trials (n = 2317) BRAF/MEK inhibitors therapy was associated with an increased risk of LVEF decrease (RR, 3.72; 95% CI, 1.74–7.94; p < 0.001) and arterial hypertension (RR, 1.49; 95% CI, 1.12–1.97; p = 0.005) compared to BRAF inhibitor monotherapy." (PMID 39859270, 2025). "Furthermore, targeted therapies, such as BRAF/MEK inhibitors, have been associated with arterial hypertension, venous thromboembolism, pulmonary embolism, and ECG abnormalities such as QTc prolongation." (PMID 37355743, 2023). "Indeed, BRAF inhibitor/MEK inhibitor treatment is associated with LVSD, systemic hypertension, atrial arrhythmia, QT interval prolongation, and venous thromboembolism." (PMID 35492830, 2022). "This supports the hypothesis whereby a “second hit” such as hypertension or ischemia is required to provoke a reduction in LVEF after exposure to BRAF inhibitor/MEK inhibitor." (PMID 35492830, 2022). "However, there is an increased risk of cardiovascular adverse events, including pulmonary embolisms, arterial hypertension and left ventricular ejection fracture with dual BRAF and MEK inhibitor therapy compared to BRAF monotherapy." (PMID 35480100, 2022). "BRAF/MEK inhibitors may cause reduction in left ventricular ejection fraction (5–11%), hypertension (11–30%) or QT interval prolongation (0–5%)." (PMID 36079112, 2022). "Cardiomyocyte BRAF is required in male mice for hypertrophy and contributes to interstitial fibrosis in hypertension induced by AngII, but it increases contractility and suppresses fibrosis in physiological hypertrophy induced by α1-adrenergic receptor stimulation with phenylephrine." (PMID 36331065, 2022). "As well as contributing to recurrent vasoconstriction and hypertension, BRAF inhibitor/MEK inhibitor–related reductions in NO bioavailability also lead to an imbalance between thrombotic and antithrombotic states and may result in thrombotic sequelae." (PMID 35492830, 2022). "These agents have been associated with a high prevalence of hypertension, which may be a result of VEGF inhibition as well as their effects on BRAF." (PMID 33793337, 2021). "Although the mechanisms leading to BRAF/MEK inhibitor-induced hypertension are incompletely defined, studies in cancer cell lines could provide some insight." (PMID 33793337, 2021). "Treatment with BRAF and MEK inhibitors was associated with an increased risk of a high-grade decrease in LVEF (RR, 2.79; 95% CI, 1.36-5.73; P = .005; I2 = 29%) and high-grade arterial hypertension (RR, 1.54; 95% CI, 1.14-2.08; P = .005; I2 = 0%)." (PMID 31397860, 2019).
Hypertension (continued). "Indeed, BRAF/MEK inhibitor–induced hypertension and the consequent elevation in cardiac afterload may amplify their direct cardiotoxic effects." (PMID 35492830, 2022). "Moreover, compared with wild-type BRAF patients, smoking status, alcohol intake, diabetes mellitus, hypertension and chronic GI conditions were not risk factors for mutant BRAF patients." (PMID 26530529, 2015). "Ten patients (45%) experienced one or more reversible grade 3 TRAE, including arterial hypertension, maculo-papular rash, and duodenal perforation (resolving spontaneously after REGO interruption, while maintaining BRAF/MEKi)." (PMID 39682270, 2024). "Systemic hypertension and LVSD are the most commonly reported CVAEs in clinical trials, and their incidence is higher with the use of combination BRAF inhibitor/MEK inhibitor therapy compared with BRAF inhibitor monotherapy." (PMID 35492830, 2022). "In the case of grade 4 hypertension (ie, hypertension with life-threatening consequences), the MEK inhibitor should be permanently discontinued, BRAF inhibitor should be temporarily stopped and hypertension treated on an urgent basis." (PMID 35492830, 2022). "Similarly, hypertension may result from BRAF and MEK effect on the renin‐angiotensin system." (PMID 33982883, 2021). "The clinical approach states that therapy with BRAF and MEK inhibitors should be stopped in case of stage 2 hypertension, defined as systolic blood pressure more than 160 mm Hg or diastolic blood pressure more than 100 mm Hg." (PMID 31397860, 2019). "Overall, 8.1% of patients from the BRAF and MEK inhibitor treatment group had a decrease in LVEF compared with only 2.0% in the control group, and 19.5% of patients in the BRAF and MEK treatment group developed arterial hypertension, compared with 14.0% in the BRAF inhibitor control group." (PMID 31397860, 2019). "Therefore, these derivatives represent promising candidates for further preclinical development as antimelanoma chemotherapeutics, especially in patients without hypertension and resistant to current BRAF-targeted strategies." (PMID 41515422, 2025). "Overall, these changes in gene expression indicate that the pathophysiological stresses resulting from AngII-induced hypertension were not ameliorated in the hearts with cardiomyocyte BRAF knockout and reduced cardiomyocyte hypertrophy and were, if anything, exacerbated." (PMID 36331065, 2022). "Most EGFR, SRC (including dasatinib), RAF (such as BRAF inhibitor HG-6-64-01), and MEK inhibitors displayed antiviral effects, while the majority of hormones, steroid hormones, immunomodulators and various drugs used to treat hypertension or heart conditions showed distinct antifibrotic scores." (PMID 34045585, 2021). "There is evidence to suggest that the MAPK pathway may be cardioprotective; BRAF and MEK inhibitors inhibit this pathway and can lead to hypertrophy, apoptosis, cardiac remodeling, and declines in LVEF as well as arterial hypertension via effects on nitric oxide production." (PMID 33982883, 2021).